IFNG (interferon gamma)
Diseases named in the same sentence as IFNG in open-access papers (continued):
Sharing a sentence is not in itself a finding about the gene and the disease.
cognitive decline (22 papers, 2013 to 2025). "The trials showed an increase in interferon gamma (IFN-γ) and CSF eotaxins, which are associated with a slower cognitive decline in AD patients and a decrease in interleukin 6 (IL-6), which is associated with inflammatory states." (PMID 40725728, 2025). "In the CSF, levels of several cytokines (e.g., IL-1β, IL-4, IL-6, IL-8, IFNγ, G-CSF, and GM-CSF) are negatively associated with AD-related progression of cognitive decline, suggesting a protective function of these factors." (PMID 38076538, 2023). "For example, in one study, it was found that higher plasma IL-12p70 and IFNg in cognitively normal individuals was associated with reduced future cognitive decline." (PMID 35505128, 2022). "In the aMCI group, higher baseline plasma levels of IL-2, sCD40L, and VEGF were associated with a lower cognitive decline, and in the AD group, higher baseline plasma levels of IFNγ, IL-5, IL-17A, IL-25, FGF, GM-CSF, and VEGF were associated with a more rapid cognitive decline." (PMID 34122046, 2021). "Higher baseline levels of IL-2, sCD40L, IL-8, and VEGF were associated with a lower annual cognitive decline in the aMCI group, and higher baseline levels of Aβ1–40, IFNγ, IL-5, IL-17A, IL-25, and FGF were associated with a rapid annual cognitive decline in the AD group." (PMID 34122046, 2021). "IFNγ, as an important cytokine, can enhance the activation state of microglia, leading to the release of inflammatory mediators such as TNF-α, interleukin-1 beta (IL-1β), and nitric oxide, all of which may cause neuronal damage and cognitive decline." (PMID 39076206, 2024). "Therefore, our results suggest that in a pathological context, where IFNγ levels may be significantly altered, its role in mediating cognitive decline may emerge as particularly important to explore." (PMID 26731444, 2016). "A different set of circulating inflammatory proteins like IFNγ and IL-12, which are hallmarks of a TH1 response, are seemingly protective against cognitive decline." (PMID 38076538, 2023). "In contrast, the AD group showed that the higher baseline levels of IFNγ (r = −0.701, p = 0.036), IL-5 (r = −0.756, p = 0.019), IL-17A (r = −0.759, p = 0.021), IL-25 (r = −0.840, p = 0.036), and FGF (r = −0.780, p = 0.013) were significantly correlated with more rapid cognitive decline." (PMID 34122046, 2021).
epilepsy (22 papers, 2015 to 2025). A brain disorder characterized by episodes of abnormally increased neuronal discharge resulting in transient episodes of sensory or motor neurological dysfunction, or psychic dysfunction. "Patients with drug‐resistant epilepsy exhibit notably lower average plasma levels of IL‐10, while average serum levels of interferon‐gamma (IFN‐γ) are significantly higher." (PMID 40103702, 2025). "It indicated the common miRNAs involved in the pathogenesis of TBI and epilepsy were also closely related to the interferon gamma signaling pathway." (PMID 36438009, 2022). "Both clinical and preclinical studies have indicated that proinflammatory cytokines, including IFNγ and TNFα, play important roles in the development of epilepsy and several neuropsychiatric disorders." (PMID 31366130, 2019). "Specifically, proinflammatory cytokines, tumor necrosis factor α (TNFα), and interferon γ (IFNγ) probably contribute to development of epilepsy (epileptogenesis, ictogenesis, and seizure-related brain damages), and several neuropsychiatric disorders." (PMID 31366130, 2019). "Multivariate regression analysis indicated that interictal concentrations of serum IL-6, IFNγ, IL-17a, IFNλ3, and CSF IL-6, IL-17a, IFNλ3 were significant biomarkers for patients with severe epilepsy." (PMID 26626560, 2015). "Among 14 cytokines, four independent biomarkers (IL-6, IFNγ, IL-17a and IFNλ3) for severe seizures in three different types of epilepsy were identified." (PMID 26626560, 2015). "For example, serum IL-1b, IL-1Ra, IL-2, IL-4, IL-6, IL-8, IFNγ, and IL-17 concentrations were observed to be elevated in patients with epilepsy." (PMID 26626560, 2015). "If VA score was applied, IL-1Ra, IL-6, IFNγ, IFNλ3 and IL-17a were severity markers in all types of epilepsy." (PMID 26626560, 2015). "Using public database, we revealed the important role for interferon gamma signaling pathway in the pathological processes associated with TBI and epilepsy, yet explanations are mostly speculative." (PMID 36438009, 2022). "Interictal serum IL-6, IFNγ, IL-17a, IFNλ3, and CSF IL-6, IL-17a, IFNλ3 could be used as potential biomarkers for severe epilepsy." (PMID 26626560, 2015). "mRNA levels of IL-6, IFNγ, IL-17a, and IFNλ3 were elevated in different types of epilepsy." (PMID 26626560, 2015). "If NHS3 was used, IL-6, IFNγ and IFNλ3 were good markers in all types of epilepsy." (PMID 26626560, 2015). "Thus, we conjecture that interferon gamma may act as a bridge from TBI to epilepsy." (PMID 36438009, 2022). "The production of interferon‐gamma (IFN‐γ) in Natural killer T cell (NKT)‐like cells exhibits a negative correlation with the duration of epilepsy." (PMID 40103702, 2025). "Elevated concentrations of interleukin-6 (IL-6), interferon-gamma (IFN-γ), and interleukin-17A (IL-17A) have been observed in the plasma during the interictal phase of epilepsy, whereas IL-1β, TNF-α, and IL-10 did not rise in comparison to a healthy group." (PMID 39861097, 2024).
head and neck cancer (22 papers, 2017 to 2025). A primary or metastatic malignant neoplasm affecting the head and neck. "Osteocalcin promotes T cell proliferation and IFNγ production, inhibiting tumor cell growth, and high expression levels of osteocalcin were associated with favorable OS in patients with head and neck carcinoma treated with the anti-PD-L1 antibody durvalumab." (PMID 38026978, 2023). "Guanylate-binding protein 1 (GBP1), an interferon-stimulated gene induced by interferon-gamma (IFN-γ), has been implicated in tumor progression and treatment resistance in various cancers, including ovarian and head and neck cancers." (PMID 40975978, 2025). "In head and neck cancer, the presence of an interferon-gamma (IFNγ) gene expression signature correlated with a better clinical response to immunotherapy." (PMID 34502458, 2021). "IFNγ signaling is often associated with a positive patient response to PD-1/PD-L1-targeted therapy in metastatic melanoma, NSCLC, head and neck cancer, gastric cancer, and urothelial carcinoma." (PMID 33193345, 2020). "The enhanced expression of IL-1β after GW5074 treatment was related to an increased phosphorylation of MEK1 and ERK1/2, indirectly confirming that activation of EGFR-downstream MEK and ERK affect IFNγ/TNFα induced chemokine secretion in head and neck cancer." (PMID 30192802, 2018). "Forth, IS scores is significantly correlated with interferon-gamma score that is predictive markers for anti-PD-1 therapy in gastric and head and neck cancer." (PMID 29051489, 2017). "Thus, the upregulated expression of CIITA, RFX5, and subsequent expression of all the classical MHC-II genes and related genes required for antigen loading and presentation observed in HPV+ head and neck carcinomas are likely a consequence of IFNγ exposure." (PMID 31394808, 2019). "Head and neck carcinoma CD44+ CSCs containing elevated levels of various cytokines, including TGFβ, has been reported to inhibit production of IFNγ, a key marker of Th1 response." (PMID 38038865, 2023). "Cell culture models based on established head and neck cancer lines have also demonstrated MHC-II expression, often in response to IFNγ, or transfection with CIITA—master regulator of MHC-II transcription." (PMID 31394808, 2019).
Hemophagocytosis (22 papers, 2010 to 2025). Phagocytosis by macrophages of erythrocytes, leukocytes, platelets, and their precursors in bone marrow and other tissues. "In particular, IFNγ was demonstrated to directly stimulate macrophage activation in vivo, instigating the onset of hemophagocytosis and possibly causing cytopenias." (PMID 33424859, 2020). "Similarly, in lymphocytic choriomeningitis virus/Rab27a-deficient mice, neutralization of IFNγ has been shown to revert CNS involvement and to reduce hemophagocytosis." (PMID 33424859, 2020). "Since IL-18 plays a major role in perpetuating hemophagocytosis, the failure of IFNγ to induce IL-18BP may constitute a fundamental pathogenetic mechanism." (PMID 20072626, 2010).
ischemia (22 papers, 2008 to 2025). A hypoperfusion of the BLOOD through an organ or tissue caused by a PATHOLOGIC CONSTRICTION or obstruction of its BLOOD VESSELS, or an absence of BLOOD CIRCULATION. "Vascular insults such as ischemia and hemorrhages rapidly mobilize IFNγ secreting leukocytes to sites of injury." (PMID 37428916, 2023). "There was a notable reduction in frequency of CD8+ IFNγ+ T cells in both groups following anti-IL-6, but the effect size was markedly greater in ischemic grafts (49.04 ± 0.52 vs. 106.74 ± 2.97 fold reduction in CD8+ IFNγ+ infiltration, control vs. ischemia, ***p < 0.001, respectively, n = 3/group)." (PMID 29410442, 2018).
psoriasis vulgaris (22 papers, 2014 to 2025). Plaque psoriasis is the most common presentation of psoriasis. "A study showed that patients with blood-heat syndrome of psoriasis vulgaris had substantially elevated levels of interferon-gamma, IL-17, IL-23, and TNF-α and significantly decreased levels of IL-4 and IL-10." (PMID 32843084, 2020). "Our coculture settings (i.e., IFNγ to stimulate KCs and an S. aureus-derived superantigen (SEB) for polyclonal T cell activation) were originally chosen to represent some of the pathophysiological conditions of psoriasis vulgaris." (PMID 31324882, 2020). "Therefore, cytokines such as IL-17A, IL-22, IL-23, and TNF-α were found to be elevated in both psoriasis vulgaris and GPP; however, GPP lesions yielded significantly higher IL-1 and IL-36, and lower IL-17A and interferon-gamma (IFN-γ) messenger RNA (mRNA) expressions, than plaque psoriasis lesions." (PMID 34445754, 2021).
ulcer (22 papers, 2012 to 2025). "Multivariate analysis showed that, positive interferon-gamma release assays (IGRAs), ≥ 4 segments involved, longitudinal ulcer, circular ulcer, and aphthous ulcer were confirmed as independent discriminating factors." (PMID 34256708, 2021). "Transcriptional analysis of biopsy tissue indicated that type II interferon, IFNG, not type I (IFNA4 and IFNB1) nor type III (IFNL1, IFNL2, IFNL3) interferons, was the prevalent interferon gene detected in ulcer lesions and 8 weeks post-healed skin." (PMID 34552595, 2021).
herpes zoster (21 papers, 2016 to 2026). A common dermal and neurologic disorder caused by reactivation of the varicella-zoster virus that has remained dormant within dorsal root ganglia, often for decades, after the patient's initial exposure to the virus in the form of varicella (chickenpox). "A 45-year-old-male with anti-IFNγ auto-antibodies and recurrent TB also suffered from recurrent herpes zoster episodes." (PMID 38203686, 2023). "Among a Taiwanese cohort of 17 patients with disseminated NTM infection and anti-IFNγ auto-antibodies, 71% also suffered from herpes zoster." (PMID 38203686, 2023). "In conclusion, patients with a recent diagnosis of herpes zoster display reduced interferon-gamma secretion from natural killer cells and frequent previous psychological stress events compared with controls." (PMID 29466462, 2018). "In contrast, the cytokine profile seems to differ during infection and vaccination, as vaccine-induced VZV-specific CD4 T-cells showed a multifunctional Th1 phenotype, whereas Th1 CD4 T-cells after acute zoster were functionally restricted and predominantly expressed IFNγ only." (PMID 39265505, 2024). "Interferon-gamma secretion from natural killer cell, psychological stress events, stress cognition scale scores and cytomegalovirus-specific cell-mediated immunity were compared between 44 patients with herpes zoster and 44 age- and gender-matched control subjects." (PMID 29466462, 2018). "The zoster vaccine increases the number of VZV specific CD4+ T cells and older adults have an increase in IFNγ after a second dose of vaccine." (PMID 30537970, 2018). "In the current study, recipients of allogeneic HSCT (34 females, 45 males) were vaccinated with adjuvanted, recombinant zoster vaccine ShingrixTM, which contains the VZV glycoprotein E. Cellular immunity against various VZV antigens was analyzed by interferon-gamma ELISpot." (PMID 35632565, 2022).
psychosis (21 papers, 2013 to 2025). "The findings of elevated IL6, IL17, and IFNγ in psychosis appear robust, as elevations are also seen in sensitivity analyses, indicating they are unlikely due to confounding or other nonspecific factors." (PMID 30407606, 2019). "In order to assess the Th1/Th2 cytokines balance between subjects with first-episode psychosis and healthy controls, we calculated the IFNγ/IL-4 ratio." (PMID 22749891, 2013). "Our previous studies have also found associations between peripheral inflammatory markers, especially interleukin 6 (IL-6) and interferon gamma (IFN-γ), and psychotic disorders." (PMID 36675612, 2023). "Mean levels of IL6 (g = 0.62), TNFα (g = 0.56), interferon-γ (IFNγ) (g = 0.32), transforming growth factor-β (g = 0.53), and interleukin-17 (IL17) (g = 0.48) were elevated in psychosis." (PMID 30407606, 2019). "Antipsychotic-naïve patients with first-episode psychosis show elevated IL6, TNFα, IFNγ, IL17, and TGFβ levels compared with healthy controls." (PMID 30407606, 2019).
scrub typhus (21 papers, 2011 to 2026). Scrub typhus is a rare dust mite-borne infectious disease caused by the Orientia tsutsugamushi bacterium and characterized clinically by an eruptive fever which is potentially serious. "Previous studies have shown increased plasma or serum levels of various cytokines in scrub typhus patients such as TNFα, IFNγ, IL-6 and IL-10, but these studies included a rather low number of patients (n = 9–55) and relatively few inflammatory mediators were examined." (PMID 24516677, 2014). "Since these cytokines are all IFNγ-induced cytokines, it is not surprising that these cytokines are released into serum samples in high concentrations in scrub typhus patients." (PMID 31906849, 2020).
Behçet’s disease (20 papers, 2010 to 2026). "In other diseases, e.g., Behcet's disease, IFNγ and tumor necrosis factor (TNF)α producton predominate." (PMID 41827822, 2026). "Notably, one study showed that PBMCs from Behçet’s disease patients had higher levels of IFNγ and IL-6 secretion compared to controls upon interphotoreceptor retinoid-binding protein (IRBP) and S-antigen stimulation." (PMID 39867889, 2024). "On the other hand, the reduced production of IFNγ by Vδ2 T cells in off-crisis SCD patients versus controls suggests chronic down-modulation of these cells, similarly to what has been described in other inflammatory disorders, such as Behcet’s disease." (PMID 31251783, 2019). "Memory CD45RO+ T cells from peripheral blood mononuclear cells (PBMCs) of patients with active Behçet disease (BD) and SLE and healthy controls were stimulated with IFNα, showing an elevated expression of IFNγ in memory CD4+ T cells in BD patients and controls, but not in SLE patients." (PMID 38164134, 2023).
brain tumor (20 papers, 2004 to 2025). "Intravenous injection of the GM-CSF-expressing T cells significantly prolonged overall survival in a murine brain tumor model and the mechanisms were associated with the increased levels of interferon-gamma (IFN-γ) in the tumor microenvironment." (PMID 37111742, 2023). "In addition, in the secretome of IL-12Fc NHQ-treated patient-derived brain tumor explants, IFNγ and its hallmark gene signature members were significantly increased." (PMID 40404625, 2025). "Fifteen days after tumor injection LPS/IFNγ-MV treated mice had a significant reduction of tumor size while mice treated with IL 4-MV significantly increased the size of their brain tumors." (PMID 30853898, 2019). "Thus, IDO1 expression in brain tumor cells is likely to be triggered when IFNγ is produced from activated T cells and/or microglia and neurons." (PMID 32117235, 2020). "The KP in brain tumors is likely triggered by IFNγ from immediate surrounding tissue." (PMID 32117235, 2020). "HLA-DR was upregulated by IFNγ on some brain tumor, EWS, and NB cell lines." (PMID 28428785, 2017). "Finally, CD270/HVEM upregulation was induced by IFNγ in some brain tumor, EWS, and NB cell lines." (PMID 28428785, 2017). "Our data suggest that increased IFNγ secretion from expanded NK cells can mediate ICAM-1 upregulation and enhanced NK cell conjugate formation in brain tumors and NB, enhancing NK cell activity in adoptive immunotherapy." (PMID 28428785, 2017). "By contrast, treatment with IFNγ resulted in enhanced sensitivity to NK cells for three cell lines, BT-12, SJ-GBM2, and NB1643 (two brain tumors and a NB, respectively)." (PMID 28428785, 2017). "In addition, although the brain tumor cell line BT-12 shows a non-significant increase in sensitivity, we observed that for three of the four NK cell donors there was an increased sensitivity after IFNγ treatment, this increase is significant if these three donors are evaluated (p = 0.0061)." (PMID 28428785, 2017).
Cryptococcal meningitis (20 papers, 2010 to 2025). Meningeal inflammation produced by cryptococcus neoformans, an encapsulated yeast that tends to infect individuals with acquired immunodeficiency syndrome and other immunocompromised states. "Adjunctive treatment with interferon gamma (IFNγ) was tried in a randomized clinical trial among patients with HIV-associated cryptococcal meningitis." (PMID 38571832, 2024). "Adjunctive therapy with recombinant IFNγ in patients with HIV-associated cryptococcal meningitis decreased fungal burden in the CSF, a marker correlated with survival." (PMID 37938547, 2023). "The therapeutic potential of IFNγ to treat HIV coinfections was supported by two Phase II trials, evaluating adjunctive IFNγ to improve treatment response to antifungals in HIV patients with cryptococcal meningitis." (PMID 29375567, 2017). "Indeed, there are strong correlations observed in cryptococcal meningitis patients between IFNγ levels and fungal burdens in the cerebrospinal fluid, where greater IFNγ levels typically correlate with reduced fungal burdens and better clinical outcomes." (PMID 39207168, 2024). "In each of these cases, patients are thought to be susceptible to cryptococcal meningitis due to the lack of IFNγ-mediated activation of macrophages leading to poor fungal killing and intracellular fungal survival." (PMID 37938547, 2023). "Therefore, the role of IFNγ as an adjunct to antifungal therapy has been investigated in trials of HIV-infected patients with cryptococcal meningitis." (PMID 29970809, 2018). "In a similar manner, subgroup analyses in HIV-associated cryptococcal meningitis suggested that the greatest benefit of a short-course IFNγ adjuvant therapy was gained among patients with a lack of Cryptococcus-specific IFNγ/TNF CD4+ T cell responses." (PMID 29375567, 2017). "For instance, mice infected with a genetically engineered C. neoformans H99 reference strain expressing the type-1 cytokine IFNγ are able to clear the infection, suggesting that IFNγ supplementation may have therapeutic benefits for treating cryptococcal meningitis." (PMID 36983532, 2023). "There is strong evidence for the importance of IFNγ in human infection cases, as phase 2 clinical trials of adjuvant IFNγ therapy in patients with HIV and cryptococcal meningitis demonstrated salutary effects with regard to fungal clearance." (PMID 41440711, 2025). "For example, the HIV-infected individuals who were treated for cryptococcal meningitis and survived, had higher levels of several immune modulators in the CSF (IFNγ, TNF-α, IL-6 and IL-8) compared to those who did not." (PMID 29970809, 2018).